CTPS2 (CTP synthase 2)
Description:
CTP synthase involved in the de novo synthesis of CTP, a precursor of DNA, RNA and phospholipids. Catalyzes the ATP-dependent amination of UTP to CTP with either L-glutamine or ammonia as a source of nitrogen. Constitutes the rate-limiting enzyme in the synthesis of cytosine nucleotides.
Synonyms: GATD5B
Tractability: Small molecule: a structure with a bound ligand is known; it has a high-quality binding pocket. PROTAC: ubiquitination databases record sites on it; its protein half-life has been measured.
Target class: Enzyme; Ligase
Gene: Protein-coding gene on chromosome X (16,587,950 to 16,712,976, reverse strand). Ensembl gene ENSG00000047230.
Subcellular location: Cytoplasm, cytosol; Nucleus
Subcellular location (Human Protein Atlas): Cytosol; Mitochondria
Pathways (Reactome):
Metabolism: Interconversion of nucleotide di- and triphosphates
Gene Ontology:
Molecular function: CTP synthase activity; identical protein binding; protein binding
Biological process: CTP biosynthetic process; pyrimidine nucleobase biosynthetic process; pyrimidine nucleotide metabolic process; 'de novo' CTP biosynthetic process; organophosphate biosynthetic process; pyrimidine nucleotide biosynthetic process
Cellular component: cytoophidium; cytoplasm; mitochondrion; nucleus; cytosol
Homologues: Orthologues: chimpanzee CTPS2 (99% identical), macaque CTPS2 (99% identical), dog CTPS2 (96% identical), pig CTPS2 (96% identical), rabbit CTPS2 (95% identical), rat Ctps2 (91% identical), mouse Ctps2 (90% identical), guinea pig CTPS2 (87% identical), tropical clawed frog ctps2 (80% identical), Drosophila melanogaster Ctps (65% identical), Caenorhabditis elegans ctps-1 (53% identical). Paralogues in human: CTPS1 (75% identical).
Diseases named in the same sentence as CTPS2 in open-access papers:
CTPS2 is named in the same sentence as 23 diseases in open-access papers, as found by Europe PMC text mining. Sharing a sentence is not in itself a finding about the gene and the disease. The quoted sentences say what the papers report.
B-cell lymphomas (2 papers, 2021 to 2023). "However, the CRISPR Cancer Dependency Map (DepMap) found that targeting of CTPS2 only mildly affects proliferation of a broad range of cancer cells, including B-cell lymphomas." (PMID 34281398, 2021). "In contrast, B-cell lymphomas expressed more substantial levels of CTPS2, and a recent study suggested that the inactivation of both CTPS1 and CTPS2 is required to fully block Epstein Barr virus–driven B-cell proliferation." (PMID 37348953, 2023).
chronic lymphocytic leukemia (2 papers, 2023 to 2024). "CTPS2 was reported as being involved in cell growth, and loss of CTPS2 may lead to cell cycle arrest and apoptosis in chronic lymphocytic leukemia cells." (PMID 39543104, 2024). "CTP synthases contribute to lymphocytes proliferation and tumorigenesis, but the role of CTPS2 in chronic lymphocytic leukemia (CLL) remains undefined." (PMID 36635772, 2023). "Yet, the role of CTPS2 had not been explored in chronic lymphocytic leukemia." (PMID 36635772, 2023).
osteosarcoma (2 papers, 2020 to 2023). A usually aggressive malignant bone-forming mesenchymal neoplasm, predominantly affecting adolescents and young adults. "CTPS2 had a profound effect on osteosarcoma metastasis and also participated in the primary immunodeficiency of herpes virus susceptible populations." (PMID 33024640, 2020). "CTPS2 has been reported to be involved in several solid tumors, such as osteosarcoma and colorectal cancer, but never in hematological malignancies." (PMID 36635772, 2023).
acute leukemia (1 paper, 2023). A clonal (malignant) hematopoietic disorder with an acute onset, affecting the bone marrow and the peripheral blood. "Multiple T lymphocyte cell lines express low levels or are negative for the expression of CTPS2 at both RNA and protein levels, including the acute leukemia T-cell line Jurkat, in which CTPS2 transcript and protein were undetectable." (PMID 37348953, 2023).
chronic leukemia (1 paper, 2023). A slowly progressing leukemia characterized by a clonal (malignant) proliferation of maturing and mature myeloid cells or mature lymphocytes. "DDR inhibition showed excellent results in preclinical testing in acute and chronic leukemia, which indicated the therapeutic potential of CTPS2 inhibition." (PMID 36635772, 2023).
CNS lymphomas (1 paper, 2021). "Given our findings that CTPS2 supports proliferation of EBV-transformed CTPS1-deficient B cells, we speculate that CTPS2 plays important roles in the CNS lymphomas observed clinically." (PMID 34281398, 2021).
colorectal cancer (1 paper, 2023). A primary or metastatic malignant neoplasm that affects the colon or rectum. "Patients with colorectal cancer accompanied by low CTPS2 expression did not receive a survival benefit from 5-fluorouracil treatment, whereas those with high expression did." (PMID 36635772, 2023).
leukemia (1 paper, 2023). A malignant (clonal) hematologic disorder, involving hematopoietic stem cells and characterized by the presence of primitive or atypical myeloid or lymphoid cells in the bone marrow and the blood. "Consistently with the hypothesis, we identified that silencing CTPS2 exhibited anti-leukemia effects and increased the activity of key kinases in the DDR pathway." (PMID 36635772, 2023).
lung adenocarcinoma (1 paper, 2022). A carcinoma that arises from the lung and is characterized by the presence of malignant glandular epithelial cells. "The results showed that the mRNA expression of CTPS2 was dramatically increased in lung adenocarcinoma samples compared with normal lung samples (P < 0.001)." (PMID 34996932, 2022). "Here, our study also showed that CTPS2 is an important gene for the prognosis of lung adenocarcinoma, it is highly expressed in patients with lung adenocarcinoma, and the prognosis is poor." (PMID 34996932, 2022). "CTPS2 and DARS2 are new signatures affecting the prognosis of lung adenocarcinoma and may be potential new treatment targets." (PMID 34996932, 2022). "However, the mechanism of CTPS2 in lung adenocarcinoma is not clear, and more research is necessary." (PMID 34996932, 2022). "Interestingly, we also found that CTPS2 and DARS2 which never be reported were associated with the increasing death risk of lung adenocarcinoma." (PMID 34996932, 2022). "The relationship between CTPS2 and DARS2 and the prognosis of lung adenocarcinoma has not been studied." (PMID 34996932, 2022).
lymphoma (1 paper, 2021). A malignant (clonal) proliferation of B- lymphocytes or T- lymphocytes which involves the lymph nodes, bone marrow and/or extranodal sites. "While our quantitative proteomic analyses identified that CTPS1 is approximately four times more abundant than CTPS2 in primary human B cells undergoing EBV-mediated growth transformation, EBV-infected lymphomas may compensate for CTPS1 deficiency by increasing CTPS2 levels and/or activity in vivo." (PMID 34281398, 2021).
T-cell lymphomas (1 paper, 2023). "Interestingly, among the different tumor cell lines of hematopoietic origin we tested, T-cell lymphomas appear to be those in which the expression of CTPS2 is the lowest or undetectable." (PMID 37348953, 2023).
Turner syndrome (1 paper, 2025). Turner syndrome is a chromosomal disorder associated with the complete or partial absence of an X chromosome. "Granulosa cells derived from patients with Turner syndrome, which exhibit impaired APJ ligand signaling, display reduced expression of CTPS2 and a shift toward the G0/G1 arrest." (PMID 40760447, 2025).
cancer (6 papers, 2021 to 2025). A tumor composed of atypical neoplastic, often pleomorphic cells that invade other tissues. "Notably, CMPK1 inhibition reduces cancer cell proliferation65while CTPS2 is implicated in DNA repair, potentially aiding the placenta in maintaining genomic stability under adverse conditions." (PMID 40825832, 2025). "In conclusion, our study is an important contribution to the understanding of the respective roles of CTPS1 and CTPS2 in cell proliferation, in particular in cancer cells, for which limited information is currently available." (PMID 37348953, 2023). "Public databases analysis of more than 1,000 inactivated cancer cell lines for CTPS1 or CTPS2 confirmed that cell growth is highly dependent of CTPS1 but less or not of CTPS2." (PMID 37348953, 2023). "The cancer cells that exhibited increased cell proliferation also showed increased activity of CTPS2." (PMID 36635772, 2023). "With the discovery of increased levels of CTPS1 in lymphoblastic as well as other cancer tissues compared to the unchanged levels of CTPS2 in malignant and healthy tissue, targeting CTPS1 has received renewed interest only recently." (PMID 35203388, 2022). "Thus, the efficacy of a treatment targeting CTPS1 might be particularly dependent on the level of CTPS2 in cancer cells." (PMID 37348953, 2023). "Altogether, the higher activity of CTPS1 may be required in vivo to rapidly meet a critical need of CTP in highly proliferating cells, like activated T lymphocytes or cancer cells, whereas CTPS2, which has a lower activity, may be rather involved in maintaining basal cellular CTP pools in general." (PMID 37348953, 2023). "Regarding pyrimidine metabolism, the upregulation of CMPK1, CMPK2, CTPS2, CAD, DHODH, and UMPS suggests a role in supporting placental growth under stress, reflecting their established functions in cancer cell proliferation." (PMID 40825832, 2025). "We observed that several cancer cell lines of T-cell lymphoid origin did not express CTPS2 such as Jurkat, MOLT-4, and HUT-78." (PMID 40957650, 2025). "Analysis of public databases of more than 1,000 inactivated cancer cell lines for CTPS1 or CTPS2 confirmed that cell growth is highly dependent on CTPS1 but not or less on CTPS2." (PMID 37348953, 2023). "CTP synthetase activity is high in proliferating cells including cancer cells; however, the respective roles of CTPS1 and CTPS2 in cell proliferation are not known." (PMID 37348953, 2023). "Taken together, these results extended our observations showing that most of the cancer cell lines tested (>1,000 different cell lines) are highly dependent on CTPS1 but not or less on CTPS2 for their survival and proliferation." (PMID 37348953, 2023).
tumor (4 papers, 2020 to 2025). "Furthermore, our experimental results with HEK and Jurkat cell lines suggest that in tumor cells expressing CTPS1 only or in association with a low expression of CTPS2 (like T cell lines), inhibition of CTPS1 could lead to the rapid death of the cells by apoptosis." (PMID 37348953, 2023). "And our observations demonstrated that CTPS2 could promote CLL cell survival through DDR pathway, suggesting an underlying molecular mechanism by which ATM functions as a tumor suppressor." (PMID 36635772, 2023). "Thus, one can hypothesize that the decreased or absence of CTPS2 expression could benefit tumor cells in particular T-cell lines providing a selective advantage." (PMID 40957650, 2025).
CTPS2 also shares sentences with these, for which no sentence is quoted: acute coronary syndrome (1 paper); acute lymphoblastic leukemia (1); acute lymphoblastic T-cell leukemia (1); colon cancer (1); coronary artery disease (1); hematological malignancies (1); lung carcinoma (1); primary immunodeficiency (1); Sezary syndrome (1).